RUFY4 (RUN and FYVE domain containing 4)
Description:
ARL8 effector that promotes the coupling of endolysosomes to dynein-dynactin for retrograde transport along microtubules. Acts by binding both GTP-bound ARL8 and dynein-dynactin. In nonneuronal cells, promotes concentration of endolysosomes in the juxtanuclear area. In hippocampal neurons, drives retrograde transport of endolysosomes from the axon to the soma. Positive regulator of macroautophagy in dendritic cells. Increases autophagic flux, probably by stimulating both autophagosome formation and facilitating tethering with lysosomes. Binds to phosphatidylinositol 3-phosphate (PtdIns3P) through its FYVE-type zinc finger. Positive regulator of osteoclast bone-resorbing activity, possibly by promoting late endosome-lysosome fusion by acting as an adapter protein between RAB7A on late endosomes and LAMP2 on primary lysosomes (By similarity).
Synonyms: FLJ46536; ZFYVE31
Tractability: No criterion of Open Targets' tractability assessment is met for any kind of drug.
Gene: Protein-coding gene on chromosome 2 (218,034,960 to 218,090,584, forward strand). Ensembl gene ENSG00000188282.
Subcellular location: Cytoplasmic vesicle, autophagosome; Lysosome
Gene Ontology:
Molecular function: dynactin binding; phosphatidylinositol-3-phosphate binding; protein binding
Biological process: autophagosome assembly; cellular response to interleukin-4; positive regulation of macroautophagy; positive regulation of retrograde axon cargo transport; multivesicular body-lysosome fusion; positive regulation of bone resorption; positive regulation of exocytosis; positive regulation of transport; vacuole organization
Cellular component: autophagosome; endolysosome; lysosome
Genetic constraint (gnomAD): Loss-of-function variants: 76 observed, 64.96 expected, observed/expected ratio (o/e) 1.17, 90% interval 0.97 to 1.42. The upper end of that interval is the gene's LOEUF score, 1.42, which puts it in group 5 of 6, group 1 being the genes least tolerant of losing a copy. Missense variants: 770 observed, 654.03 expected, observed/expected ratio (o/e) 1.18, 90% interval 1.11 to 1.25. Synonymous variants: 287 observed, 246.32 expected, observed/expected ratio (o/e) 1.17, 90% interval 1.06 to 1.28.
Homologues: Orthologues: chimpanzee RUFY4 (93% identical), macaque RUFY4 (88% identical), pig RUFY4 (72% identical), dog RUFY4 (67% identical), mouse Rufy4 (62% identical), rat Rufy4 (58% identical), rabbit RUFY4 (57% identical). Paralogues in human: FYCO1 (30% identical).
Diseases named in the same sentence as RUFY4 in open-access papers:
RUFY4 is named in the same sentence as 10 diseases in open-access papers, as found by Europe PMC text mining. Sharing a sentence is not in itself a finding about the gene and the disease. The quoted sentences say what the papers report.
breast carcinoma (1 paper, 2021). "In this study, the prognostic risk model consisting of six ARGs (VPS35, TRIM21, PRKAB2, RUFY4, MAP1LC3A and LARP1) in breast cancer were identified." (PMID 34001111, 2021). "In conclusion, we identified a novel autophagy-related prognostic risk model consisting of six encoding gene (VPS35, TRIM21, PRKAB2, RUFY4, MAP1LC3A and LARP1) in breast cancer." (PMID 34001111, 2021).
osteoporosis (1 paper, 2024). A condition of reduced bone mass, with decreased cortical thickness and a decrease in the number and size of the trabeculae of cancellous bone (but normal chemical composition), resulting in increased fracture incidence. "Thus, RUFY4 plays as a new regulator in osteoclast activity by mediating endo-lysosomal trafficking and have a potential to be specific target for therapies against bone-loss diseases such as osteoporosis." (PMID 38744829, 2024).
renal carcinoma (1 paper, 2022). A carcinoma arising from the epithelium of the renal parenchyma or the renal pelvis. "Moreover, the immunohistochemical results from the Human Protein Atlas (HPA is a resource for many areas of biomedical research, including protein science and biomarker discovery) also showed that RUFY4 was highly expressed in renal cancer." (PMID 35135552, 2022).
tumor (3 papers, 2021 to 2025). "Remarkably, after narrowing the search scope to genes that were highly expressed in tumor tissues, LAG3, PDCD1, and RUFY4 were found to be associated with the high degree of immune infiltration of Tregs and TFHs." (PMID 35135552, 2022). "Among IIRGs of TFHs and TREGs, RUFY4 was found to be highly activated in tumor microenvironment and its co-expression network was enriched in PDL1/PD1 checkpoint pathway in cancer." (PMID 35135552, 2022). "Our study establishes a Tumor Microenvironment-derived Prognostic Model (MPM) that integrates eight TME-associated genes (CXCL12, GZMB, ITPR2, LYN, RAB9B, RGMB, RUFY4, TRIM16) to stratify AML patients into distinct risk categories with significant survival differences." (PMID 40608798, 2025). "We hypothesized that the immune cells in TME might be involved in the tumor-promotive function of RUFY4 based on the findings that RUFY4 functioned little on migration and invasion of ccRCC." (PMID 35135552, 2022). "Besides, RUFY4 had an activated expression in tumor tissues, hence could accurately and sensitively distinguish between normal and ccRCC patients." (PMID 35135552, 2022). "To explain this conflict phenomenon, we make a hypothesis that the immune system might be involved in the tumor-promotive function of RUFY4 based on the following evidence: (a) Metastasis is under the control of complex and redundant pathways involving the tumor cell and the microenvironment." (PMID 35135552, 2022). "Furthermore, the expression level of RUFY4 could predict the responsiveness of tumor patients to ICB immunotherapy." (PMID 35135552, 2022). "Moreover, we analyzed the correlation among four-gene signature (FeSig) (BID, TAZ, MT1G, and SLC7A11), downstream hub genes (CPNE7, WNT10B, ADAMTS14, and RUFY4), and immune checkpoints (PD-1, CTLA4, LAG3, and TIGIT) to further discover potential molecular mechanisms of tumor immunity." (PMID 34367965, 2021).
cancer (2 papers, 2022). A tumor composed of atypical neoplastic, often pleomorphic cells that invade other tissues. "Our findings suggest that the functions of RUFY3 in neurons and cancer cells, and RUFY4 in phagocytic cells, might be related to the ability of these proteins to couple endolysosomes to dynein-dynactin." (PMID 35314674, 2022). "Indeed, processes such as the regulation of axonal functions, cancer cell migration, invasion and metastasis, and autophagy have all been shown to be influenced by endolysosome positioning and motility, consistent with a role for RUFY3 and RUFY4 in the regulation of endolysosomal functions." (PMID 35314674, 2022).
bacterial infection (1 paper, 2021). "RUFY4 expression has been shown to increase the resistance of cells to intracellular bacterial infection such as B. abortus and of S. typhimurium." (PMID 34295519, 2021). "By optimizing effector proteins activity and organelles distribution, RUFY4 expression facilitates the elimination of intracellular bacteria like Brucella abortus, and Salmonella typhimurium replication, suggesting that it has a role in the cell response to bacterial infection." (PMID 34295519, 2021).
bone disorder (1 paper, 2024). "Our study provides new insights into the molecular mechanisms governing osteoclast activity and underscores Rufy4’s potential as a novel therapeutic target for bone disorders characterized by excessive bone resorption." (PMID 39513873, 2024).
RUFY4 also shares sentences with these, for which no sentence is quoted: infection (1 paper); ischemic stroke (1); primary immunodeficiency (1).